RAP1A (RAP1A, member of RAS oncogene family)
Diseases named in the same sentence as RAP1A in open-access papers (continued):
Sharing a sentence is not in itself a finding about the gene and the disease.
tumor (45 papers, 2009 to 2026). "Rap1A encoded protein regulates signaling pathways that affect cell proliferation and adhesion, which plays a role in tumor malignancy." (PMID 32226523, 2020). "We show here that PI3Kγ activates PLCγ, leading to RasGrp/CalDAG-GEF-I&II mediated, Rap1a-dependent activation of integrin α4β1, extravasation of monocytes and granulocytes, and inflammation-associated tumor progression." (PMID 23565202, 2013). "We have show here that PI3Kγ activates PLCγ, leading to RasGrp/CalDAG-GEF-I&II mediated, Rap1a-dependent activation of integrin α4β1, extravasation of myeloid cell, and inflammation-associated tumor progression." (PMID 23565202, 2013). "Rap1A and RalA are Ras subfamily members and are associated with endothelial cell adhesion and tumor genesis, respectively." (PMID 23028658, 2012). "While most studies have focused on tumor or platelet systems, direct targeting of Rap1A and Rap1B by miRNAs has also been demonstrated in endothelial cells." (PMID 40508181, 2025). "• Collectively, Rap1a is presently given due considerationfor exhaustive exploration to confirm its role in cellular proliferation(GBM tumor growth)." (PMID 35786935, 2022). "Krev-1=rap1a in turn functions as a tumor-suppressor protein by binding to a number of the effectors of the Ras oncogene." (PMID 34824953, 2021). "In order to detect the MAPK-RAP1A pathway, we detected the expression of ERK, JNK, p38, and RAP1A by tissue RT-qPCR and found that the expression of ERK, JNK, p38, and RAP1A in HCC tumor tissues was higher than that in adjacent tissues." (PMID 34178637, 2021). "In order to elucidate the role of the signature genes’ biological functions, the association of STMN1, RAP1A, FLT3, HSPA8, ANGPT2, and PGF was positively associated with tumor purity in HCC." (PMID 34178637, 2021). "KIF14 also participates in modulating components of adhesion on the tumor cell surface, regulating migration and invasion through Rap1a-Radil signaling, thereby promoting cell motility during metastasis." (PMID 33033514, 2020). "We found that the Milan criteria, TNM stage, tumor size, nodules numbers, microvascular invasion and donor Rap1A rs494453 genotypes turn out to be significant determinants for HCC recurrence after LT." (PMID 32226523, 2020). "Although some studies emphasized the roles of Rap1A and Rap1B in tumor progression, little has been reported on the functional differences between these two isoforms." (PMID 32906721, 2020). "The restoration of EYA4 expression in HCC cell lines suppressed cell proliferation, inhibited clonogenic outgrowth, reduced cell invasion and restrained xenograft tumor growth, and Flag-RAP1A reversed the suppressive effects of pEYA4 in vitro." (PMID 29764501, 2018). "Taken together, these evidences collectively suggest that RAP1A is a key oncoprotein in tumor development and therefore can serve as a potential therapeutical target for cancer patients." (PMID 30064475, 2018). "In our experiments, HOS and U2OS cells treated with VPA and ZOL were shown to express significantly higher level of unprenylated Rap1A than ZOL alone in immunofluorescence, while tumor cells treated with VPA alone hardly express unprenylated Rap1A." (PMID 29535738, 2018). "Accordingly, the mice intraperitoneally injected with Rap1A shRNA expressing cells had a reduced metastasis tumor by at least one order of magnitude and with a higher weight than control mice." (PMID 27925454, 2016). "As shown by Western blotting, unprenylated Rap1A was undetectable in tumor cells treated only with US." (PMID 26578234, 2015). "The expression levels of Rap1A mRNA were higher in cancer tissues compared with matched adjacent non-tumor tissues." (PMID 25636908, 2015). "All these proved that Rap1A is a functional target of miR-203 and this evidence suggested that miR-203 exerts its tumor-suppressive effects through downregulation of Rap1A in PCa cells." (PMID 25636908, 2015).
tumor (continued). "Our studies demonstrate that chemoattractants stimulate myeloid cell RTK, GPCR and TIR-receptor-mediated integrin α4β1 activation, myeloid cell tumor trafficking and tumor inflammation and growth by promoting PI3Kγ-dependent Rap1a activation." (PMID 23565202, 2013). "This implicates Rap1A in tumorigenesis before the cancer has spread to the nodes (Stage I) as well as during tumor metastasis (Stages II–IV)." (PMID 23405264, 2013). "Similar to blockade of PI3Kγ or integrin α4β1, blockade of Rap1a suppressed both the recruitment of monocytes and granulocytes to tumors and tumor progression." (PMID 23565202, 2013). "In vivo, tumor-derived chemoattractants promote the recruitment and infiltration of myeloid cells to the tumor microenvironment by increasing PI3Kγ-Rap1a-integrin α4β1-dependent adhesion to the tumor endothelium." (PMID 23565202, 2013). "Having observed that Rap1A depletion inhibited invasive properties of tumor cells, we next assessed if the depletion of endogenous Rap1A also blocked LPA-stimulated MDA-MB-231 cell migration." (PMID 23405264, 2013). "As further details of the Rap1a-integrin α4β1 pathway are revealed, it is likely that new targets and therapies for the suppression of tumor inflammation will be developed." (PMID 23565202, 2013). "In vivo, tumor-derived chemoattractants promote the recruitment and infiltration of myeloid cells to the tumor microenvironment in PI3Kγ-Rap1a-integrin α4β1-dependent adhesion to the tumor endothelium." (PMID 23565202, 2013). "Blockade of either integrin α4β1 or Rap1a suppresses tumor inflammation, angiogenesis and tumor progression in murine models of cancer." (PMID 23565202, 2013). "Additionally, the association of Rap1A and Krit1 in cytoskeletal regulation and the presence of STAT1, linked to the urea cycle and tumor development, offered insights into Lucena 1’s distinctive biology." (PMID 39272999, 2024). "Rap1a expression was elevated in GBM and associated with higher tumor grade." (PMID 32102991, 2020). "A recent study further demonstrated that Rap1A expression abolished the tumor-suppressive effects of EYA4 in HCC cells, which could promote the proliferation and recurrence." (PMID 32226523, 2020). "In clinical studies, Rap1A is not only overexpressed in a cohort of Oral Cavity Squamous Cell Carcinoma (OCSCC) specimens but also correlated with the clinical characteristics of the advanced tumor stage 13." (PMID 32226523, 2020). "Interestingly, Rap1a has been shown to be important for cellular proliferation in the context of in vivo GBM tumor growth." (PMID 32102991, 2020). "In GBM, Rap1a expression was increased compared to non-tumor tissue using the TCGA database." (PMID 32102991, 2020). "We found RAP1A expression was significantly correlated with tumor invasion (p = 0.045)." (PMID 30064475, 2018). "In subcutaneous models, tumor tissues in ZOL or VPA + ZOL treated BALB/c-nu mice showed marked unprenylated Rap1A and Ras expression, which were demonstrated in immunofluorescence and western blotting, while these unprenylated proteins were hardly detected in VPA-treated or untreated xenografts." (PMID 29535738, 2018). "As a surrogate assay for tumor‐initiating ability, we tested the formation of cell spheres in three‐dimensional cultures at clonal densities that recapitulate the function of Rap1A in cell self‐renew and proliferation to closely mimic the in vivo physiological situation that favors stem cell growth." (PMID 27925454, 2016). "Rap1A is a tumor suppressor which mediates growth inhibitory responses in cancer." (PMID 27092172, 2016). "Unprenylated Rap1A was barely detectable following a 1-h ZOL treatment of tumor cells." (PMID 26578234, 2015). "To validate whether miR-203 exerts its tumor-suppressive function through Rap1A, we knocked down Rap1A by RNA interference techniques." (PMID 25636908, 2015).
tumor (continued). "All these indicate that miR-203 functions as tumor suppresser through inhibiting Rap1A in PCa and miR-203 may be used in clinical applications for cancer." (PMID 25636908, 2015). "Importantly, this contention was supported by the observation that ZOL+US induced accumulation of unprenylated Rap1A in tumor extracts at D8, contrary to D15." (PMID 26578234, 2015). "As Rap1A is reported to function as an oncogene, this may indicate that miR-203 suppresses tumor metastasis through inhibiting Rap1A." (PMID 25636908, 2015). "All data elucidate a new mechanism that miR203 suppresses tumor growth through inhibiting Rap1A." (PMID 25636908, 2015). "In the studies described here, we found that Rap1a is required to promote integrin α4β1-dependent myeloid cell trafficking during inflammation and tumor growth in vivo, as we observed substantial suppression of tumor growth and inflammation in mice transplanted with Rap1a−/− bone marrow." (PMID 23565202, 2013). "This led to RAP1A over-expression resulting in more aggressive tumor behavior." (PMID 23752272, 2013). "Similar reductions in tumor growth and inflammation were also observed in Rap1a−/− animals." (PMID 23565202, 2013). "To further understand the molecular basis by which ZA inhibited the differentiation of tumor-induced MDSCs into osteoclasts, we analyzed the prenylation of two small GTPase, Rap1A and Rab6, which are important intracellular signaling proteins that are activated by prenylation." (PMID 23173040, 2012). "Importantly, mice transplanted with Rap1a−/− BM exhibited significantly reduced tumor growth." (PMID 23565202, 2013). "Together, these results indicate that Rap1a is an important mediator of tumor inflammation and progression through its actions on integrin activation during the recruitment of myeloid cells to the tumor microenvironment, with subsequent effects on tumor angiogenesis." (PMID 23565202, 2013). "Previous studies have demonstrated that RAP1A activates PI3K, leading to AKT phosphorylation and subsequent mTOR activation, which in turn regulates tumor resistance, proliferation, and survival." (PMID 41328352, 2026). "Myeloid cell trafficking to tumours depends on PI3Kγ‐mediated integrin activation, and subsequent myeloid cell recruitment and tumour inflammation depend on PLCγ, CalDAG‐GEFI and II, Rap1a, RIAM, talin, paxillin and myosin light chain kinase." (PMID 40434054, 2025). "RBM10 can also reduce the activation of RAP1A and decrease phospho‐AKT and phospho‐CREB to inhibit tumor proliferation." (PMID 33718153, 2021). "Firstly, RAP1A expression was abnormally higher in CRC tissues as compared with adjacent normal tissues, and significantly correlated tumor invasion." (PMID 30064475, 2018). "Since CEA is the most commonly examined tumor marker for CRC patients, we then integrated its preoperative level with RAP1A expression in prognostic analysis." (PMID 30064475, 2018). "Measurements of unprenylated small G-proteins (i.e., Rap1A) and IPP in ZOL-treated tumor cells have been therefore used as surrogate markers of bisphosphonate antitumor activity." (PMID 26578234, 2015). "Here we show that PI3Kγ-mediated integrin activation and subsequent myeloid cell recruitment and tumor inflammation depends on PLCγ, CalDAG-GEFI and II, Rap1a and RIAM." (PMID 23565202, 2013). "Interestingly, STMN1 and ANGPT2 were significantly positively correlated with tumor purity, whereas RAP1A, FLT3, HSPA8, and PGF were all significantly negatively correlated with tumor purity." (PMID 34178637, 2021). "The effect that Rap1a activity has on GBM patient survival is likely to be complex, and not simply one in which increased Rap1a expression increases tumor invasion and thus decreases patient survival." (PMID 32102991, 2020). "RAP1A is a molecular switch that activates downstream MAPK signalling pathways and promotes the expression of several target molecules that participate in the development of tumours and other diseases." (PMID 31316002, 2019).
tumor (continued). "The concentrations of compound 7 required to stimulate production of TNF-α release were not significantly correlated with those required for RAP1A inhibition nor were tumor cell growth inhibition and RAP1A inhibition correlated." (PMID 28729550, 2017). "To determine the impact of myeloid cell Rap1a on tumor inflammation and progression, we evaluated the growth of LLC tumors in WT mice that were lethally irradiated and transplanted with bone marrow from WT or Rap1a−/− mice." (PMID 23565202, 2013). "In addition, Rap1A expression is elevated in GBM and correlates with higher tumour grade." (PMID 34576182, 2021). "Consequently, they found that cells transfected with miR-433 associated decreased Rap1a protein levels along with slightly lowered Rap1a mRNA levels, thus demonstrating that, by targeting the RAP1A gene and subsequently activating the MAPK signaling pathway, miR-433 behaves as a tumor suppressor." (PMID 33194751, 2020). "However, we did not detect any difference in the prenylation of Rap1A and Rab6 in the Gr-1+/CD11b+cells from spleen of either non-treated or ZA-treated tumor-bearing mice." (PMID 23173040, 2012). "One way to reconcile these counterintuitive findings is to consider the possibility that Rap1a may have different roles in GBM CSCs versus non-CSCs, as well as unknown effects on tumor progression in vivo versus cell culture." (PMID 32102991, 2020).
cancer (33 papers, 2006 to 2025). A tumor composed of atypical neoplastic, often pleomorphic cells that invade other tissues. "Survival analysis results revealed a strong association between RAF1 and RAP1A expression levels and diminished survival rates in cancer patients across different cancer types." (PMID 39498560, 2025). "Through predictive algorithms and molecular simulations, we identified deleterious mutations in RAF1 and RAP1A, shedding light on their impact on cancer patient survival." (PMID 39498560, 2025). "In previous studies, HSPA8 and RAP1A have been demonstrated to be associated with cancer growth and proliferation in various human cancers." (PMID 35193578, 2022). "Rap1a has been linked to cell division, proliferation, apoptosis and the differentiation of the stages of cancer." (PMID 34743742, 2021). "Rap1A is a GTPase that belongs to the Ras-associated protein (Rap) family, which is similar to Ras mostly 16, and associated with cancer initiation and progression." (PMID 32226523, 2020). "Nonetheless, exosomal proteins previously reported to be associated with vesicle secretion in cancer cell line supernatants (RAP1A, RAP1B, VAMP1, MYH7, MYO18a, MYOLPF, MYO1E, VPS13B, HSP70) were identified in our samples." (PMID 30764491, 2019). "As one of the Ras‐associated proteins, Rap1A has been linked to cancer initiation and development." (PMID 27925454, 2016). "In this study, we wanted to know how RAP1A SNPs affected its interaction with RAF1 and their role in cancer susceptibility and development." (PMID 39498560, 2025). "RAP1A is a protein belonging to the Ras subgroup, which is widely studied for its contribution to the malignant progression of numerous human cancers, including GBM." (PMID 38542389, 2024). "The RAP1 signaling pathway regulates multiple biological processes, including cancer metastasis, and the GTPase RAP1A affects cell adhesion, intercellular junctions, and cell polarity." (PMID 36895029, 2023). "Another enriched cancer-related pathway is VEGFA-VEGFR2 Signaling Pathway which was enriched by RAP1A, SH3BGRL3, and ITGB1." (PMID 35176998, 2022). "The expression of TLN1 and TLN2 was positively associated with CNV in most cancers, except for APBB1IP, RAP1B, and RAP1A." (PMID 33391455, 2021). "It was also reported that RAP1A regulates cancer through activating MAPK signaling in order to regulate motility and metastasis." (PMID 34178637, 2021). "RAP1A signaling is involved in cell proliferation, differentiation, and cell–cell junction in several cancer types." (PMID 34178637, 2021). "Among them, the MAPK and RAP1A are the mediator pathways in regulating cell biology of cancer cells." (PMID 34178637, 2021). "Rap1A is a member of Ras oncogene family of small G protein, which regulates different cellular processes, including proliferation, adhesion and cancer progression." (PMID 32226523, 2020). "Decreasing Rap1A suppressed cell proliferation, adhesion, and invasion in prostate cancer and several other cancer types 11-13." (PMID 32226523, 2020). "The mechanism investigations also suggest several micoRNAs (such as miR-196a and miR-203) exert their oncogenic or anti-cancer roles through targeting RAP1A." (PMID 30064475, 2018). "Similar with these members, RAP1A has recently been found to involve in the development of various cancers, however its specific role in CRC remains poorly investigated." (PMID 30064475, 2018). "In glioblastoma, RAP1A is essential for thrombin-stimulated proliferation of cancer cells, which can be attributed to its activating role in integrin/ERK or B-Raf/ERK signaling." (PMID 30064475, 2018). "In the present study, we have assessed bisphosphonate prodrug activation of Vγ2Vδ2 T cells and inhibition of RAP1A prenylation in response to a variety of human cancer cell lines pretreated with the compounds." (PMID 28729550, 2017). "Many studies have shown that Rap1A was upregulated and involved in cell-cell and cell-extracellular matrix adhesion in many cancers." (PMID 25636908, 2015).